CLLU1 (chronic lymphocytic leukemia up-regulated 1)
Gene: Long non-coding RNA gene on chromosome 12 (92,421,531 to 92,431,002, forward strand). Ensembl gene ENSG00000257127.
Subcellular location: Cytoplasm
Diseases named in the same sentence as CLLU1 in open-access papers:
CLLU1 is named in the same sentence as 4 diseases in open-access papers, as found by Europe PMC text mining. Sharing a sentence is not in itself a finding about the gene and the disease. The quoted sentences say what the papers report.
chronic lymphocytic leukemia (4 papers, 2016 to 2021). "CLLU1 mainly acts as a stable and inherent diagnostic biomarker of chronic lymphocytic leukemia and is significantly associated with poor clinical outcomes." (PMID 30916406, 2019). "One of those genes – CLLU1 – has been shown earlier to be specifically expressed in chronic lymphocytic leukemia (CLL)." (PMID 27437030, 2016). "Lastly, some of these probes were also annotated to intergenic regions and to a gene with unknown function (CLLU1) that has mainly been studied in the context of chronic lymphocytic leukemia." (PMID 33771206, 2021). "This study evaluates the impact of CLLU1 expression and fluorescent in situ hybridization (FISH) analysis of a group of Turkish chronic lymphocytic leukemia (CLL) patients." (PMID 29129824, 2018).
SAPHO syndrome (1 paper, 2021). SAPHO syndrome (acronym for Synovitis, Acne, Pustulosis, Hyperostosis and Osteitis) is an auto-inflammatory disease, mainly characterized by the association of neutrophilic cutaneous involvement and chronic osteomyelitis. "The ROC curve of GAS7 and Lnc-CLLU1.1-1:2 indicated that such pair may be a promising biomarker of SAPHO syndrome." (PMID 34234815, 2021).
tumor (1 paper, 2019). "Another study further found LINC00309 with other two gene dernicidin (DCD1) and Chronic lymphocytic leukemia up-regulated 1 (CLLU1) were specific expression in tumor." (PMID 31406486, 2019).
CLLU1 also shares sentences with these, for which no sentence is quoted: hepatocellular carcinoma (1 paper).